CFH (complement factor H)
Diseases named in the same sentence as CFH in open-access papers (continued):
Sharing a sentence is not in itself a finding about the gene and the disease.
posterior uveitis (2 papers, 2012 to 2023). Inflammation of the choroid as well as the retina and vitreous body. "A C3b to CFH ratio was computed to assess the regulation of complement activation and this index was several folds higher in both anterior and posterior uveitis (n=10 each)." (PMID 38187376, 2023). "The expression of miRNA-hsa-miR-146a and miRNA-hsa-miR-155-5p that regulates CFH was downregulated and nicely correlated with the increased complement proteins in both anterior and posterior uveitis (n=10 each)." (PMID 38187376, 2023). "We also evaluated the estimation of major alternative complement pathway components, namely, C3 and CFH, in the aqueous and vitreous humor of anterior and posterior uveitis patients, as well as their expression and regulation by miRNAs." (PMID 38187376, 2023). "Our results demonstrated that CFH-rs800292 and KIAA1109-rs4505848 were significantly associated with IU and posterior uveitis, and in particular Behçet’s disease." (PMID 22876110, 2012). "In the case of posterior uveitis, upregulation of both C3 and CFH genes could be an indicator of a blood-retinal breakdown (BRB)." (PMID 38187376, 2023). "Downregulation of C3 and CFH mRNA in the peripheral blood was shown by quantitative PCR in the group of anterior uveiits (AU), while the opposite result was found in the group of posterior uveitis (PU)." (PMID 38187376, 2023). "In this study, CFH-rs800292 was found to be associated with non-infectious intermediate and posterior uveitis, which showed a recessive effect (GG/AG versus AA; p=0.02, OR=2.74)." (PMID 22876110, 2012). "The frequency of carriers of G allele for CFH-rs800292 was significantly higher in patients with non-infectious intermediate and posterior uveitis than in controls (GG/AG versus AA; p=0.02)." (PMID 22876110, 2012). "A higher expression of C3b and lower expression of CFH in the vitreous humor samples of patients with posterior uveitis could be explained by the fact that a larger part of the uvea tends toward the posterior end of the eye where the inflammation is in the ciliary body, choroid, and retina." (PMID 38187376, 2023). "Our results demonstrated that CFH-rs800292 and KIAA1109-rs4505848 are associated with non-infectious intermediate and posterior uveitis." (PMID 22876110, 2012). "In this study, we investigated the association of three immune-related SNPs in the CFH, KIAA1109, and IL27 genes with non-infectious intermediate and posterior uveitis." (PMID 22876110, 2012). "In conclusion, we identified the associations of CFH-rs800292 and KIAA1109-rs4505848 with non-infectious intermediate and posterior uveitis in Chinese patients." (PMID 22876110, 2012). "Taking together, we hypothesize that CFH-rs800292, IL-27-rs4788084, and rs4505848 within the KIAA1109/Testis nuclear RNA-binding protein (Tenr)/IL2/IL21 gene cluster might be involved in the pathogenesis of IU and posterior uveitis." (PMID 22876110, 2012).
prostate carcinoma (2 papers, 2008 to 2012). A carcinoma that arises from epithelial cells of the prostate gland. "The finding of CFH and CFHR1 up-regulation in PP adipose tissue of subjects with prostate cancer suggests increased inhibitory modulation of the complement activity in prostate tumor cells and evasion to attack." (PMID 23009291, 2012).
pulmonary fibrosis (2 papers, 2021 to 2024). Chronic progressive interstitial lung disorder characterized by the replacement of the lung tissue by connective tissue, leading to progressive dyspnea, respiratory failure, or right heart failure. "Collectively, these data indicated that CFH and FHL2 are involved in the pulmonary fibrosis and activation of fibroblasts induced by bleomycin and TGFβ1, respectively." (PMID 38784225, 2024).
retinal detachment (2 papers, 2017 to 2020). An eye emergency condition which may lead to blindness if left untreated. "Eyes with CFH protective allele against AMD tend to spontaneously resolve without treatment within 3 months after the occurrence of serous retinal detachment secondary to CSC while the serous retinal detachment tends to be prolonged more than 3 months in CSC with CFH risk allele for AMD." (PMID 32610483, 2020).
Splenomegaly (2 papers, 2019 to 2022). Abnormal increased size of the spleen. "Finally, a previous study utilizing complement factor H (CFH)-deficient mice reported the development of splenomegaly with distorted spleen architecture." (PMID 36670923, 2022).
Ss (2 papers, 2024). "Our study found that CFH in Synovial Sarcoma is correlated with some genes undergoing m6A methylation." (PMID 38549939, 2024). "The results showed that the AUC value for the CFH gene reached 1, a perfect prediction result, demonstrating the high accuracy of the CFH gene in the diagnosis and prognostic evaluation of synovial sarcoma." (PMID 38549939, 2024). "These discoveries emphasize the potential key role that CFH could play in the occurrence and development of Synovial Sarcoma, especially by potentially regulating the expression of tumor-related genes through the process of m6A methylation." (PMID 38549939, 2024). "This indicates that the CFH gene may play a significant role in synovial sarcoma." (PMID 38549939, 2024). "In Synovial Sarcoma, we also identified the key gene CFH, although the role of CFH in Synovial Sarcoma has not yet been reported." (PMID 38549939, 2024).
temporal lobe epilepsy (2 papers, 2012 to 2023). A localization-related (focal) form of epilepsy characterized by recurrent seizures that arise from foci within the temporal lobe, most commonly from its mesial aspect. "A miR-146a–CFH–IL-1β loop circuit was found to initiate a cascade of inflammation in temporal lobe epilepsy." (PMID 37996918, 2023).
thrombosis (2 papers, 2019 to 2024). "This protein is encoded by the THBD gene and variants including A43T (Impaired binding of Complement factor H (CFH) and C3b), P495S and P501L (Moderate reduction of thrombomodulin expression on the cell surface) and D486Y (Less common in patients with venous thrombosis) are identified." (PMID 38198013, 2024). "This study also reveals lower complement factor H protein levels among subjects with SLE and thrombosis." (PMID 31134052, 2019).
urinary tract infection (2 papers, 2015 to 2020). "FDA-approved Complement factor H, which has been reported for the diagnosis of patients with benign renal diseases and urinary tract infections as well as other cancer types, provides only 60% specificity." (PMID 25915536, 2015).
acute lung injury (1 paper, 2020). A condition of lung damage that is characterized by bilateral pulmonary infiltrates (pulmonary edema) rich in neutrophils, and in the absence of clinical heart failure. "Together, these data demonstrate that CFH can stimulate the NLRP3 inflammasome in macrophages and that this pathway may be important in the pathogenesis of CFH‐induced acute lung injury." (PMID 33128438, 2020).
adult-onset Still disease (1 paper, 2024). A rare inflammatory multisystem disorder characterized clinically by fever of unknown origin, arthralgia or arthritis, hyperleucocytosis, and typical skin rash. "We presented an unusual case of adult-onset Still’s disease (AOSD) with macrophage activation syndrome (MAS), which is in fact associated with anti-complement factor H (anti-CFH) antibodies related aHUS." (PMID 38745129, 2024).
bacterial meningitis (1 paper, 2019). Inflammation of the membranes surrounding the brain and spinal cord due to a bacterial infection. "To determine whether genetic variance in CFH influences outcome of bacterial meningitis, we performed a genetic association study of four common functional single nucleotide polymorphisms (SNP) in CFH (rs6677604, rs1065489, rs3753394, rs800292)." (PMID 31883521, 2019).
bone metastasis (1 paper, 2024). Transfer of a neoplasm from its primary site to bones. "Next, we analysed immune cell infiltration in patients with PCa and with or without bone metastasis, finding a positive correlation between CFH, APOC1 and LGALS1 and various immune cell types." (PMID 39098992, 2024).
C. perfringens infection (1 paper, 2025). "Moreover, the findings underscore a coordinated effort of the host to mitigate the C. perfringens infection via activating immune (a.o., C3, CFH, MASP2, MBL2) and acute phase (CP, ORM, TF, ExFAB) related proteins." (PMID 40275387, 2025).
co-infection (1 paper, 2024). "The complement factor H protein showed the highest abundance in the co-infection groups compared to single infection groups." (PMID 38803570, 2024). "The increased abundance in the co-infection groups indicates that the complement factor H protein likely contributes to tissue haemostasis and the immune response of rainbow trout against myxozoan co-infections." (PMID 38803570, 2024).
coagulopathy (1 paper, 2025). "Remarkably, main hub proteins in the CR group were VTN, C3, C4B, C9, and CFH that play a major role in the complementary pathway, which has gained increased attention as a major contributor to cancer‐related coagulopathy." (PMID 40079446, 2025).
fungal infection (1 paper, 2020). "The presence of negative regulators, CFH and CFI, in the patient tear indicate that the complement activity is tightly regulated during fungal infection." (PMID 32435625, 2020).
hepatoblastoma (1 paper, 2022). Hepatoblastoma (HB) is a malignant hepatic tumor and is the most common pediatric liver cancer. "circ-CFH could function as a miR-1250-3p sponge to regulate cell viability, proliferation, and invasion of hepatoblastoma cells in vitro." (PMID 35415236, 2022).
Hypercholesterolemia (1 paper, 2010). An increased concentration of cholesterol in the blood. "ORs were adjusted for age, gender, tobacco smoking, hypercholesterolemia, and CFH and ARMS2 genotypes." (PMID 20664795, 2010).
infectious anterior uveitis (1 paper, 2023). An infectious disease involving a pathogenic inflammatory response in the anterior uvea. "Quantitative real-time PCR was performed for the candidate genes, i.e., C3 and CFH, in the peripheral leukocytes of patients with non-infectious anterior uveitis and control subjects." (PMID 38187376, 2023).
infectious posterior uveitis (1 paper, 2023). "Quantitative real-time PCR for the candidate genes, i.e., C3 and CFH, in the peripheral leukocytes showed an upregulation of both C3 and CFH genes (FC-4.5 ± 0.8; * p = 0.04 and FC-7.09 ± 1.1; *p = 0.04 respectively) in the patients with non-infectious posterior uveitis as compared to controls." (PMID 38187376, 2023).
intracerebral hemorrhage (1 paper, 2023). A cerebrovascular disorder characterized by bleeding into one or both cerebral hemispheres including the basal ganglia and the cerebral cortex. "The CFH rs1061170 independently predicted mortality at discharge and 6 months and survival duration after spontaneous intracerebral hemorrhage (p = 0.019; p = 0.041, respectively)." (PMID 37803932, 2023).
leprosy (1 paper, 2020). Leprosy is a chronic infectious disease affecting primarily the skin and peripheral nervous system. "Moreover, this study also found two variants of the CFH gene, which showed significant associations with leprosy, indicating the involvement of the alternative complement pathway in leprosy pathogenesis." (PMID 32373110, 2020).
Listeria infection (1 paper, 2021). "Eight of these genes were similarly inhibited by Listeria infection in PMH: they encode (i) the activating enzyme C1S of the C1 complex, (ii) the central component C3, (iii) the membrane-attack proteins C6 and C8A, and (iv) four complement regulators (C1QTNF6, CFH, CFHR2, VTN)." (PMID 34858876, 2021).
liver failure (1 paper, 2022). A liver disease characterized by the liver losing or has lost all of its function. "The liver is one of the predominant producers of CfH and ApoJ, but incidence of liver failure was low in our studied population." (PMID 36606279, 2022).
lymphoma (1 paper, 2025). A malignant (clonal) proliferation of B- lymphocytes or T- lymphocytes which involves the lymph nodes, bone marrow and/or extranodal sites. "In the present case, we describe a patient with lymphoma and MIg-C3GN who exhibited both a monoclonal IgM kappa M-spike and autoantibodies targeting complement C3 convertase and complement factor H (CFH)." (PMID 40342409, 2025).
malignant hypertension (1 paper, 2023). Severe hypertension that is characterized by rapid onset of extremely high blood pressure and hypertension-mediated organ damage. "While demographics were similar, patients with aHUS + malignant hypertension had an increased need for renal replacement therapy, including kidney transplantation (47% vs 32%), and more pathogenic variants/anti-complement factor H antibodies (56% vs 37%) than those without malignant hypertension." (PMID 36152218, 2023).
myocardial infarction (1 paper, 2007). Gross necrosis of the myocardium, as a result of interruption of the blood supply to the area, as in coronary thrombosis. "In 2006, Kardys and colleagues investigated the role of the Y402H polymorphism in the CFH gene and reported an increased risk for myocardial infarction in those who were homozygous for the His variant." (PMID 17877809, 2007).
myopic maculopathy (1 paper, 2021). "Complement Factor H presented higher levels as myopic maculopathy developed, and both macular atrophy and neovascularization significantly increased compared to the eyes that looked normal (p ˂ 0.05)." (PMID 34204630, 2021).
neuroendocrine tumors (1 paper, 2019). "These include CHGA (also associated with neuroendocrine tumors), CFH, SPP1, and an immunoglobulin-like receptor." (PMID 30678299, 2019).
osteoarthritis (1 paper, 2023). A noninflammatory degenerative joint disease occurring chiefly in older persons, characterized by degeneration of the articular cartilage, hypertrophy of bone at the margins and changes in the synovial membrane. "We found that CFH was significantly higher in serum or synovial fluid of RA patients compared with those of healthy controls (606.6±185.8 μg/ml vs 472.4±96.7 μg/ml, p=0.0003) or osteoarthritis patients (126.8±29.2 μg/ml vs 46.5±16.3 μg/ml, p=0.0005)." (PMID 37996918, 2023).
osteoporosis (1 paper, 2025). A condition of reduced bone mass, with decreased cortical thickness and a decrease in the number and size of the trabeculae of cancellous bone (but normal chemical composition), resulting in increased fracture incidence. "Secondary analysis further confirmed the potential association of WNT2B rs3737136, CFH rs12401515, and DNM3 rs1576340 with osteoporosis-related traits, but their association with RCTs was not replicated in the present study." (PMID 40866365, 2025).
otitis media with effusion (1 paper, 2022). Otitis media associated with accumulation of fluid in the middle ear. "Of note, high CFHR5 levels have been observed in otitis media with effusion which was hypothesized to compete with CFH for binding of C3b enabling rapid enhancement of complement activation." (PMID 36194022, 2022).
periodontal diseases (1 paper, 2025). "CFH polymorphisms are also linked to an increased risk of inflammatory diseases, including cardiovascular and periodontal diseases, particularly in the elderly." (PMID 41356214, 2025).
relapsing fever (1 paper, 2009). Relapsing fever is an infection caused by bacteria of the genus Borrelia, excluding those responsible for Lyme disease belonging to the Borrelia burgdorferi complex. "In summary, this is the first study showing the simultaneous and non-competitive binding of CFH and PLG to the outer surface protein HcpA of B. recurrentis, the agent of louse-borne relapsing fever." (PMID 19308255, 2009).
renal fibrosis (1 paper, 2023). A final common manifestation of a wide variety of chronic kidney diseases characterized by glomerulosclerosis and tubulointerstitial fibrosis. "We observed a dynamic decrease in uromodulin and CFH protein levels, which were associated with the development of renal fibrosis and C3 deposition." (PMID 37047611, 2023).
retinoblastoma (1 paper, 2018). A malignant tumor that originates in the nuclear layer of the retina. "Moreover, the genetic variant rs1061170 (p.Y402H) in CFH which is a strong risk factor for AMD seems to influence the levels of ceramides in serum, and FHL-1 variants Y402 and H402 differentially regulate the expression of ceramide synthesis genes in retinoblastoma-derived cells." (PMID 30071029, 2018).
retinopathy of prematurity (1 paper, 2017). A bilateral retinopathy characterized by neovascularization, scarring, retinal detachment, and eventually blindness. "Estimated haplotype frequencies of the significantly associated variants in CETP, CFH, and FBLN5 genes in retinopathy of prematurity (ROP) and premature controls." (PMID 29312345, 2017).
skin cancer (1 paper, 2022). "Most relevant to this work, cultured cSCC respond to both CFH and CFI and the receptor for the more potent C5a can be detected in skin tissue and is expressed in skin cancer lines." (PMID 35223500, 2022).
squamous cell lung carcinoma (1 paper, 2022). A carcinoma arising from squamous bronchial epithelial cells. "Specifically, in addition to its role in cSCC, a role for CFH has been described for hepatocellular and clear cell renal cell carcinomas (ccRCC) but not does not appear to promote squamous cell lung carcinoma." (PMID 35223500, 2022).
Stickler syndrome (1 paper, 2014). Stickler syndrome is an inherited vitreoretinopathy characterized by the association of ocular signs with more or less complete forms of Pierre-Robin sequence, bone disorders, and sensorineural deafness (10% of cases). "Our analysis of the human RPE secretome yielded two tyrosine-sulfated proteins, complement factor H (CFH) and collagen type 2 (alpha 1), which are implicated in AMD and Stickler syndrome, respectively." (PMID 25136834, 2014).
thalassemia (1 paper, 2026). An inherited blood disorder characterized by a decreased synthesis of one of the polypeptide chains that form hemoglobin. "Mutations in the complement factor H (CFH) gene are associated with the development of aHUS; however, CFH gene mutations coexisting with thalassemia have rarely been reported." (PMID 42125085, 2026). "Here, we report a case of pregnancy-associated aHUS in a patient with thalassemia and a CFH gene mutation." (PMID 42125085, 2026).
trypanosomiasis (1 paper, 2021). Infection with protozoa of the genus trypanosoma. "Additional genes highlighted in our study were CFH, TRNT1, IL5RA, MGAT4C and NTS, which could be also relevant for the trypanosomiasis resistance in cattle." (PMID 34351956, 2021).
tuberculosis (1 paper, 2025). A chronic, recurrent infection caused by the bacterium Mycobacterium tuberculosis. "Of identified core proteins, complement factor H formed a diagnostic classifier that distinguished latent Mtb infection from healthy controls with good performance, and we also identified C4B, MBL2, SAA1, and matrix Gla protein as potential proteomic signatures of active tuberculosis." (PMID 40736242, 2025).
Tubulointerstitial nephritis (1 paper, 2015). "Tubulointerstitial nephritis antigen-like precursor (TINAGL1), was linked to complement proteins, complement C3 (C3) and complement factor H (CFH) in a separate cluster." (PMID 26083627, 2015).
type 1 diabetes (1 paper, 2021). "Hepatocyte growth factor activator, complement factor H, ceruloplasmin, and age predicted progression time to type 1 diabetes significantly better than age alone." (PMID 33668851, 2021).
upper respiratory tract infections (1 paper, 2015). "As is frequently seen, carriers of CFH mutations may remain well for many years before presenting with aHUS following an initiating trigger, such as upper respiratory tract infections, fevers, pregnancy, drugs and non E. coli diarrheal illnesses." (PMID 25925370, 2015).